ALK (ALK receptor tyrosine kinase)
Diseases named in the same sentence as ALK in open-access papers (continued):
Sharing a sentence is not in itself a finding about the gene and the disease.
non-small cell lung carcinoma (continued). "For example, anaplastic lymphoma kinase (ALK) rearrangements are found in 2–7% of non-small-cell lung cancer (NSCLC) patients." (PMID 41216191, 2025). "Rearrangements of the anaplastic lymphoma kinase (ALK) gene are present in 3 to 5% of non-small cell lung cancers (NSCLCs)." (PMID 39796163, 2025). "Drugs for cancers that are resistant to prior therapies include ceritinib (indication: ALK-positive non-small cell lung cancer (NSCLC) resistant to crizotinib) and ponatinib hydrochloride (indication: chronic myelogenous leukaemia resistant to prior therapy)." (PMID 38167464, 2024). "Anaplastic lymphoma kinase (ALK) inhibitors are currently the recommended first-line treatment for ALK-rearranged metastatic non-small cell lung cancer (NSCLC) according to the National Comprehensive Cancer Network guidelines." (PMID 38961982, 2024). "Translocations of the Anaplastic Lymphoma Kinase (ALK) gene represent an actionable genomic alteration in 5–8% of Non-Small Cell Lung Cancer (NSCLC) patients." (PMID 38448512, 2024). "Selective anaplastic lymphoma kinase (ALK) tyrosine kinase inhibitors (TKIs) have transformed ALK-rearranged non-small cell lung cancer therapy (NSCLC)." (PMID 37322261, 2024). "Lorlatinib is a pharmaceutical ALK kinase inhibitor used to treat ALK driven non-small cell lung cancers." (PMID 39056757, 2024). "The types and number of ALK-positive tumors are increasing year by year, including anaplastic thyroid carcinoma, non-small cell carcinoma and so on." (PMID 38403820, 2024). "With an objective response rate of 60% in ALK-positive non-small cell lung cancer and a progression-free survival of 7 to 10 months, it is superior to standard first-line pemetrexed plus platinum chemotherapy and has an advantage of clinical validation." (PMID 38233857, 2024). "Further clinical research is warranted to validate lorlatinib's efficacy and safety profile, thereby advancing personalized treatment options and improving outcomes for patients with ALK-positive non-small cell lung cancer." (PMID 39677236, 2024). "Considering the role of ALK in non-small-cell lung cancer, our findings suggest potential pathways for further exploration of the miRNA regulation of ALK in cancer progression." (PMID 39684787, 2024). "ALK inhibitors have shown substantial efficacy in treating ALK-positive cancers, particularly for non-small cell lung cancers." (PMID 39728071, 2024). "The mutation of EGFR is the major factor associated with non-small cell lung carcinoma (NSCLC), in addition to a frequent mutation of KRAS and fusion of anaplastic lymphoma kinase (ALK)." (PMID 39056802, 2024). "The remarkable therapeutic efficacy of crizotinib makes ALK-rearranged non-small cell lung cancer a manageable chronic disease and extended lifespan of these patients." (PMID 37733896, 2024). "Currently, we have three generations of ALK inhibitors available for patients with non-small-cell lung cancer." (PMID 39457620, 2024). "Anaplastic lymphoma kinase (ALK) inhibitors are the recommended treatment of ALK-rearranged non-small cell lung cancer but are prone to eventual drug resistance." (PMID 38961982, 2024). "While tyrosine kinase inhibitors (TKI) have shown remarkable efficacy in anaplastic lymphoma kinase (ALK) fusion-positive advanced non-small cell lung cancer (NSCLC), clinical outcomes vary and acquired resistance remains a significant challenge." (PMID 38407352, 2024). "Crizotinib, a tyrosine kinase inhibitor, shows efficacy in the treatment of ALK-positive or ROS1-positive non-small cell lung cancer (NSCLC) and refractory inflammatory myofibroblastic tumors (IMTs) with ALK mutations." (PMID 39001541, 2024). "Anaplastic lymphoma kinase (ALK) rearrangement, the most common oncogenic rearrangement in lung adenocarcinoma, occurs in approximately 5% of non-small cell lung cancer (NSCLC) patients." (PMID 39735595, 2024).
non-small cell lung carcinoma (continued). "Non-small cell lung carcinoma (NSCLC) therapy has been transformed by the identification of actionable oncogenic driver mutations, of which ALK, ROS1, RET fusions and MET exon 14 skipping represent interesting drug targets." (PMID 38492039, 2024). "The evaluation and management of non-small cell lung cancer (NSCLC) have dramatically evolved since the discovery of oncogenic driver mutations, such as anaplastic lymphoma kinase (ALK)." (PMID 38835344, 2024). "Lorlatinib displays marked systemic and intracranial efficacy against anaplastic lymphoma kinase (ALK) positive non-small cell lung cancer (NSCLC)." (PMID 38903993, 2024). "In 2007, EML-ALK, the ALK fusion gene, was found to be present in 3%–7% of patients with non-small-cell lung cancer, triggering the research and development boom of ALK personalized medicine." (PMID 38674402, 2024). "By integrating molecular biology, chemistry, and clinical research, researchers identified its efficacy against specific molecular pathways, leading to targeted therapies for ALK-positive non-small cell lung cancer." (PMID 39335535, 2024). "This has also been reported in neoplasms of other lineages, most notably ALK-rearranged non-small-cell lung cancer (NSCLC)." (PMID 38397186, 2024). "Alectinib, as adjuvant therapy, demonstrated favorable efficacy and manageable safety in patients with completely resected ALK-positive stage I B-IIIB non-small cell lung cancer." (PMID 39497711, 2024). "EGFR mutations, ALK translocations, ROS1 aberrations and BRAF mutations are now routinely evaluated in advanced non-small cell lung cancer (NSCLC), especially in adenocarcinoma." (PMID 38200537, 2024). "Driver mutations in tyrosine kinases, such as the anaplastic lymphoma kinase (ALK) mutation, are known to play a critical role in the pathogenesis of non-small cell lung cancer (NSCLC) but are rarely observed in large cell neuroendocrine carcinoma (LCNEC)." (PMID 39723252, 2024). "This systematic review and meta-analysis aimed to evaluate the neurocognitive adverse events (NAEs) related to lorlatinib in patients with ALK/ROS1-positive non-small cell lung cancer (NSCLC)." (PMID 39061249, 2024). "An anaplastic lymphoma kinase (ALK) inhibitor called brentinib is used to treat ALK-positive non-small cell lung cancer." (PMID 38262996, 2024). "Ceritinib, marketed as Zykadia® by Novartis, is an approved targeted therapy for anaplastic lymphoma kinase (ALK)-positive non-small cell lung cancer (NSCLC) patients." (PMID 38399413, 2024). "Background and Objective: This review comprehensively explores the intricate landscape of anaplastic lymphoma kinase (ALK), focusing specifically on its pivotal role in non-small cell lung cancer (NSCLC)." (PMID 38397899, 2024). "Lorlatinib, an anaplastic lymphoma kinase (ALK)–inhibitor, is approved as frontline as well as subsequent line of therapy in ALK-rearranged advanced non-small cell lung cancer (NSCLC)." (PMID 38439810, 2024). "A few of the examples quoted include Osimertinib for EGFR mutated NSCLC (non-small-cell lung cancer) and ALK (anaplastic lymphoma kinase) inhibitors for ALK-positive NSCLC." (PMID 38578776, 2024). "The tyrosine kinase inhibitor alectinib is currently the first-line treatment for advanced ALK-positive non-small cell lung cancer." (PMID 39061248, 2024). "SAF-189s is a potent ALK/ROS1 inhibitor that is currently in clinical development for treating advanced ALK+/ROS1+ non-small cell lung cancer (NSCLC)." (PMID 39081957, 2024). "Anaplastic lymphoma kinase (ALK) gene rearrangements occur in 3% to 5% of patients with non-small cell lung cancer (NSCLC) and confer sensitivity to treatment with ALK tyrosine kinase inhibitors (TKIs)." (PMID 39197358, 2024). "Genetic translocations resulting in gene fusions are common in ALK-dependent human cancers, including non-small cell lung cancer, diffuse large B cell lymphoma, squamous cell carcinoma, and renal cell carcinoma." (PMID 38231572, 2024).
non-small cell lung carcinoma (continued). "Crizotinib 1 is an approved first generation ALK inhibitor (IC50 vs. EML4-ALK = 250–300 nM) used to treat ALK-positive non-small cell lung cancer (NSCLC)." (PMID 38338677, 2024). "As a result of pursuing treatment for oligoprogression, a request was made to access to CERITINIB (which was studied in Non-Small Cell Lung Cancer (NSCLC) with ALK rearrangement) through an expanded access program in 2014, but was refused in November." (PMID 39931211, 2024). "Liquid biopsy can also identify ALK (Anaplastic Lymphoma Kinase) rearrangements in cancers such as non-small cell lung cancer (NSCLC), offering insights into treatment strategies." (PMID 38398189, 2024). "ALK genes have been investigated in a multifarious oncological spectrum, including ALK-positive anaplastic large cell lymphomas, non-small cell lung cancer, spitzoid neoplasms, inflammatory myofibroblastic tumors, and epithelioid fibrous histiocytomas." (PMID 39202049, 2024). "For brain metastases (BMs) from EGFR/ALK-positive non-small cell lung cancer (NSCLC), the best time to administer tyrosine kinase inhibitors (TKIs) and brain radiotherapy (RT) has not been identified." (PMID 38262977, 2024). "In solid tumors, ALK rearrangements are most commonly observed in non-small cell lung cancer (NSCLC), occurring in about 3–8% of cases." (PMID 39594806, 2024). "To date, there are only 2 globally documented instances of non-small cell lung cancer (NSCLC) with concurrent SMARCA4 deficiency and mutations in EGFR or ALK." (PMID 39465834, 2024). "Ensartinib has shown significantly greater efficacy in ALK positive non-small cell lung cancer patients when compared to crizotinib (25.8 and 12.7 months respectively) and clinical trials are currently in place for pHGGs harboring ALK, NTRK and ROS1 fusions." (PMID 38525424, 2024). "The ALTA-1 L trial and EXP-3B arm of NCT01970865 trial found that both brigatinib and lorlatinib showed durable and robust responses in treating ALK-positive non-small cell lung cancer (NSCLC) patients." (PMID 38435286, 2024). "Patients with ALK-rearranged non-small cell lung cancer (NSCLC) who are treated with ALK tyrosine kinase inhibitors (ALK TKIs) have better prognoses." (PMID 39911820, 2024). "This is the case for EGFR-mutant or ALK-rearranged non-small cell lung cancer inhibitors, tucatinib and trastuzumab–deruxtecan for HER2-positive breast cancer and BRAF inhibitors for melanoma." (PMID 38893253, 2024). "Anaplastic lymphoma kinase (ALK) rearrangements account for 5–6% of all non-small cell lung cancer (NSCLC) cases and are caused by the fusion of ALK with other partner genes." (PMID 39066355, 2024). "Examples of cancers in which the presence of rearrangements within the ALK gene has been confirmed include non-small-cell lung cancer, breast cancer, colorectal cancer, kidney cancer, ovarian cancer and esophageal cancer." (PMID 39457620, 2024). "The anaplastic lymphoma kinase (ALK) gene harbors rearrangements in approximately 4-6% of non-small cell lung cancer (NSCLC) cases." (PMID 38738001, 2024). "Molecular testing for ALK fusion can be performed as part of standard clinical care in non-small cell lung cancer, primarily adenocarcinoma, from both tumor tissue and plasma samples." (PMID 38605928, 2024). "Over 30 targeted drugs, including EGFR inhibitors and ALK inhibitors, are extensively used in the clinical treatment of non-small cell lung cancer (NSCLC), and use of these drugs has resulted in a substantial prolongation of patient survival." (PMID 39085398, 2024). "The aim of this commentary is to highlight data from clinical trials, case reports, and case series evaluating alectinib in patients with early-stage ALK-positive non-small cell lung cancer in the adjuvant and perioperative setting." (PMID 39061248, 2024). "The identification of ALK fusions in advanced non-small-cell lung carcinoma (aNSCLC) is mandatory for targeted therapy." (PMID 38927925, 2024).
non-small cell lung carcinoma (continued). "At present, the prognostic significance of ALK gene in postoperative non-small cell lung cancer patients remains controversial." (PMID 39497711, 2024). "Ensartinib, an approved ALK inhibitor, is used as a first-line therapy for advanced ALK-positive non-small cell lung cancer in China." (PMID 38789868, 2024). "It has been approved by the U.S. FDA and in clinical practice as a targeted therapy for ALK-positive non-small cell lung cancer (NSCLC)." (PMID 39134539, 2024). "Anaplastic lymphoma kinase (ALK) fusions account for 5–7% of non-small cell lung cancer (NSCLC) patients, the therapeutic approaches for which have significantly evolved in the last few years." (PMID 39063924, 2024). "Crizotinib is an oral small-molecule tyrosine kinase inhibitor of the ALK, MET, and ROS1 kinases, approved in ALK-positive non-small cell lung cancer." (PMID 38928438, 2024). "ALK inhibitors have shown significant activity in ALK-positive tumors, especially in non-small-cell lung cancer." (PMID 38254833, 2024). "ALK-rearranged non-small cell lung cancer treatment has radically changed in the last few years thanks to the development of ALK inhibitors, which clearly improved survival." (PMID 37444532, 2023). "The most studied ALK-positive disease is non-small cell lung cancer, and three generations of ALK tyrosine kinase inhibitors (TKIs) have been approved for the treatment of metastatic disease." (PMID 37954850, 2023). "The evidence of anaplastic lymphoma kinase (ALK) inhibitor for non-small cell lung cancer (NSCLC) harbouring sperm antigen with calponin homology and coiled-coil domains 1-like (SPECC1L)-ALK fusion was limited." (PMID 38234623, 2023). "GAB1 has been described to be involved in alectinib resistance mediated by activation of the HGF/MET signaling pathway in anaplastic lymphoma kinase (ALK)-positive non-small cell lung cancer." (PMID 37627207, 2023). "Lorlatinib (LRL) is the first drug of the third generation of anaplastic lymphoma kinase (ALK) inhibitors used a first-line treatment of non-small cell lung cancer (NSCLC)." (PMID 37175262, 2023). "As of March 2023, ALK inhibitors have been covered by health insurance only for some non-small cell lung cancers and anaplastic large cell lymphoma in Japan." (PMID 37656266, 2023). "Based on these compelling findings, lorlatinib was identified as a potentially effective treatment for patients with ALK-positive non-small cell lung cancer (NSCLC) while exhibiting an expected safety profile during phase I and phase II trials." (PMID 37513921, 2023). "With the exception of NTRK and RET fusions, all of the US FDA approvals are tumor-specific: ALK (non-small cell lung cancer [NSCLC]), ROS1 (NSCLC), and FGFR2-3 (urothelial, cholangiocarcinoma)." (PMID 37853341, 2023). "Alectinib has been shown to have a high response rate and prolonged progression-free survival in ALK-rearranged non-small cell lung cancer (NSCLC)." (PMID 37113357, 2023). "Recent research on ALK+ non-small cell lung cancer sheds light on HER3’s significant role in resistance." (PMID 38239350, 2023). "It is now widely accepted that ALK inhibitors are effective drugs in the treatment of ALK-positive non-small cell lung cancer (NSCLC)." (PMID 37175262, 2023). "Anaplastic lymphoma kinase (ALK)-tyrosine kinase inhibitors rarely elicit complete responses in patients with advanced ALK-rearranged non-small cell lung cancer (NSCLC), as a small population of tumor cells survives due to adaptive resistance." (PMID 36702855, 2023). "The hazard ratio for progression-free survival of ALK-TKIs increased in patients with ALK fusion-positive non-small cell lung cancer with FGFR1- and FGF2-high mRNA expression at baseline." (PMID 37880373, 2023).
non-small cell lung carcinoma (continued). "Examples include the use of imatinib (Gleevec) for chronic myelogenous leukemia, crizotinib and other anaplastic lymphoma kinase (ALK) inhibitors for non-small-cell lung cancers, and trastuzumab and lapatinib for ERBB2/HER2 amplified breast cancers." (PMID 36809237, 2023). "ALK (anaplastic lymphoma kinase) gene rearrangement occurs in approximately 4.5% of non-small cell lung cancer (NSCLC) patients." (PMID 36896848, 2023). "It is a novel ALK inhibitor that has been approved for advanced ALK-positive non-small cell lung cancer indications following treatment with crizotinib." (PMID 37445800, 2023). "ALK inhibitors are currently used to treat first-line metastatic non-small cell lung cancer with ALK rearrangement." (PMID 37894307, 2023). "Alectinib has been approved as first-line treatment for anaplastic lymphoma kinase (ALK)-positive non-small cell lung carcinoma." (PMID 37663243, 2023). "Ceritinib is used to treat anaplastic lymphoma kinase (ALK)-rearranged non-small cell lung cancer, which inhibits RANKL-induced phosphorylation of Akt and p65 in osteoclast and improves trabecular bone loss in OVX-mice." (PMID 37860014, 2023). "In fact, numerous, alternate fusion partners have been documented following the discovery of ALK translocations, for example EML4-ALK-positive non-small-cell lung cancer (NSCLC) and other solid tumours." (PMID 37414143, 2023). "Recently, systemic therapies have become a part of the treatment paradigm, particularly for patients with ALK-rearranged non-small cell lung cancer." (PMID 38012621, 2023). "Central nervous system (CNS) metastases and acquired resistance complicate the treatment of anaplastic lymphoma kinase (ALK) rearrangement-positive (ALK-p) advanced non-small cell lung cancer (NSCLC)." (PMID 36768562, 2023). "Brigatinib is an anaplastic lymphoma kinase (ALK) inhibitor approved for the treatment of ALK-positive non-small cell lung cancer." (PMID 37052729, 2023). "ALK is also frequently rearranged (EML4–ALK) in some solid tumors particularly non-small-cell lung carcinoma (NSCLC)." (PMID 36909156, 2023). "Non-small cell lung cancers (NSCLCs) with anaplastic lymphoma kinase (ALK)-rearrangement have favorable responses to ALK inhibitors." (PMID 37706178, 2023). "One of targets is abnormal anaplastic lymphoma kinase, which results from the rearrangement of the ALK gene in patients with non-small cell lung cancer (NSCLC)." (PMID 36896848, 2023). "ALK fusions, particularly the EML4-ALK fusion, are recognized as oncogenic drivers in a subset of non-small cell lung cancers." (PMID 37705755, 2023). "A list of selected phase 3 clinical trials evaluating the efficacy of ALK inhibitors in non-small cell lung cancer." (PMID 37954850, 2023). "Small molecules targeting aberrant anaplastic lymphoma kinase (ALK) are active against ALK-positive non-small-cell lung cancers and neuroblastoma." (PMID 37765282, 2023). "In metastatic non-small cell lung cancer (NSCLC) harboring driver mutations (e.g., EGFR, ALK, or ROS1), targeted therapies are usually preferred over other approaches since they have been found effective and to have tolerable toxicity." (PMID 37370869, 2023). "The ALTA-1L study compared brigatinib with crizotinib in untreated ALK-rearranged non-small cell lung cancer (NSCLC) patients, demonstrating the efficacy of brigatinib." (PMID 37749521, 2023). "ALK tyrosine kinase inhibitors (TKI) have revolutionized the treatment of ALK+ non-small cell lung cancer (NSCLC), and therapy resistance occurs in virtually all patients." (PMID 37722715, 2023). "Non-small-cell lung cancer (NSCLC) is often associated with mutations in receptor tyrosine kinases, such as EGFR and ALK." (PMID 38140117, 2023). "Specific inhibitors, such as crizotinib, ceritinib, alectinib, etc., are highly beneficial in treating ALK-positive individuals, particularly those with non-small cell lung cancer." (PMID 37568193, 2023).